PTGIS (prostaglandin I2 synthase)
Description:
Catalyzes the biosynthesis and metabolism of eicosanoids. Catalyzes the isomerization of prostaglandin H2 to prostacyclin (= prostaglandin I2), a potent mediator of vasodilation and inhibitor of platelet aggregation. Additionally, displays dehydratase activity, toward hydroperoxyeicosatetraenoates (HPETEs), especially toward (15S)-hydroperoxy-(5Z,8Z,11Z,13E)-eicosatetraenoate (15(S)- HPETE).
Synonyms: CYP8; CYP8A1; PGIS; PTGI
Tractability: Small molecule: a structure with a bound ligand is known; it has a high-quality binding pocket. Antibody: UniProt predicts a signal peptide or a membrane-spanning region. PROTAC: a small molecule that binds it is known.
Target class: Cytochrome P450; Cytochrome P450 8A1; Enzyme; Cytochrome P450 family 8; Cytochrome P450 family 8A
Gene: Protein-coding gene on chromosome 20 (49,503,874 to 49,568,157, reverse strand). Ensembl gene ENSG00000124212.
Subcellular location: Endoplasmic reticulum membrane
Subcellular location (Human Protein Atlas): Endoplasmic reticulum; Cytosol; Golgi apparatus
Pathways (Reactome):
Metabolism: Eicosanoids; Synthesis of Prostaglandins (PG) and Thromboxanes (TX)
Gene Ontology:
Molecular function: heme binding; hydroperoxy icosatetraenoate dehydratase activity; prostaglandin-I synthase activity; protein binding; iron ion binding; monooxygenase activity; oxidoreductase activity, acting on paired donors, with incorporation or reduction of molecular oxygen
Biological process: apoptotic signaling pathway; cellular response to hypoxia; cellular response to interleukin-1; cellular response to interleukin-6; icosanoid metabolic process; negative regulation of inflammatory response; negative regulation of nitric oxide biosynthetic process; positive regulation of angiogenesis; positive regulation of execution phase of apoptosis; positive regulation of peroxisome proliferator activated receptor signaling pathway; prostaglandin biosynthetic process; prostanoid biosynthetic process; cyclooxygenase pathway; lipid metabolic process; monocarboxylic acid biosynthetic process
Cellular component: caveola; endoplasmic reticulum; nucleus; endoplasmic reticulum membrane; cytoplasm; endoplasmic reticulum lumen
Genetic constraint (gnomAD): Loss-of-function variants: 49 observed, 54.24 expected, observed/expected ratio (o/e) 0.9, 90% interval 0.72 to 1.15. The upper end of that interval is the gene's LOEUF score, 1.15, which puts it in group 5 of 6, group 1 being the genes least tolerant of losing a copy. Missense variants: 667 observed, 679 expected, observed/expected ratio (o/e) 0.98, 90% interval 0.92 to 1.05. Synonymous variants: 260 observed, 272.25 expected, observed/expected ratio (o/e) 0.96, 90% interval 0.86 to 1.06.
Homologues: Orthologues: chimpanzee PTGIS (99% identical), macaque PTGIS (97% identical), dog PTGIS (86% identical), mouse Ptgis (86% identical), pig PTGIS (85% identical), rat AABR07054614.1 (81% identical), guinea pig PTGIS (76% identical), tropical clawed frog ptgis (56% identical), zebrafish ptgis (46% identical). Paralogues in human: CYP8B1 (41% identical).
Diseases named in the same sentence as PTGIS in open-access papers:
PTGIS is named in the same sentence as 90 diseases in open-access papers, as found by Europe PMC text mining. Sharing a sentence is not in itself a finding about the gene and the disease. The quoted sentences say what the papers report.
lung carcinoma (13 papers, 2007 to 2024). "The role of PTGIS in osteosarcoma has not yet been reported, but some studies have demonstrated that PTGIS is associated with the prognosis of bladder and lung cancers." (PMID 37190333, 2023). "The level of PTGIS was lower in lung cancer compared with the normal tissues and is associated with a variety of immune markers and the survival of patients with lung cancer." (PMID 37415224, 2023). "High PTGIS is associated with poorer overall survival and progression-free survival of lung cancer." (PMID 39165641, 2024). "PTGIS has been implicated in the progression of stomach, ovarian, and lung cancers." (PMID 37796199, 2023). "However, among the other three common solid tumors (colorectal cancer, ovarian cancer, and lung cancer), high PTGIS expression was associated with a worse prognosis than low PTGIS expression." (PMID 32463792, 2020). "The expression of PTGIS was absolutely lower in bladder cancer, cervical cancer, colorectal cancer, head and neck cancer, leukemia, lung cancer, ovarian cancer, and prostate cancer than in normal samples." (PMID 32463792, 2020). "In another study, overexpression of PTGIS inhibited lung cancer progression." (PMID 35513851, 2022). "Although studies of PTGIS are still few, it is known that PTGIS may play an important role in tumorigenesis and cancer development in colon cancer, lung cancer, breast cancer, and head and neck cancer." (PMID 32463792, 2020). "According to previous studies, the murine orthodox lung cancer model’s occurrence and progression are inhibited by elevated PGI2 concentration brought on by PTGIS overexpression." (PMID 37256175, 2023). "Related studies have shown that the expression levels of PTGIS and PGI2 in lung cancer are significantly higher than those in the normal control group, which is consistent with our results." (PMID 32340320, 2020).
pulmonary hypertension (11 papers, 2007 to 2024). Increased pressure within the pulmonary circulation due to lung or heart disorder. "In this 2-stage genetic association study of 230 patients with idiopathic pulmonary arterial hypertension, heterozygous rare PTGIS variants were first found significantly overrepresented in 6.1%, conferring 7.8 higher odds of pulmonary arterial hypertension." (PMID 32236489, 2020). "Prior research has indicated that mutations within the PTGIS gene could potentially heighten the vulnerability to pulmonary hypertension." (PMID 37796199, 2023). "It has been demonstrated previously that PTGIS can inhibit cell growth in lung to alleviate pulmonary hypertension and overexpression of PTGIS in human embryonic kidney epithelial 293 (HEK-293) cell line can induce cell death." (PMID 29892223, 2018). "Some polymorphisms and their haplotypes in the promoter region of the PTGIS gene have been identified as affecting its expression and they might influence the pathogenesis of pulmonary hypertension." (PMID 36835616, 2023).
breast carcinoma (10 papers, 2015 to 2023). "Index patient 2 presented three likely pathogenic variants SLC3A1 c.1400T > C, MAT1A c.826dupG, and PTGIS c.824G > A. Breast cancer cells have elevated expression of SLC3A1, which accelerates cysteine uptake and accumulates reduced glutathione and decreases reactive oxygen species in tumor cells." (PMID 37628631, 2023). "Furthermore, other studies suggested that PTGIS variants may affect breast cancer susceptibility, and elevated PTGIS was associated with liver metastasis and poor survival outcomes for patients with colon cancer." (PMID 32463792, 2020). "Studies have revealed that differential expression of the PTGIS gene is closely related to the pathological and physiological processes of many diseases, including breast cancer, oral squamous cell carcinoma, and head and neck cancer." (PMID 37779109, 2023). "PTGIS as one of fatty acid-related genes, patients whose breast cancer tissues express high levels of PGIS have a lower 10-year survival rate." (PMID 36785673, 2023). "PTGIS, PTGES, and PTGER4 up-regulation in the group of responders with HER2-positive breast cancer, known by its aggressive behavior, is associated with complete tumor response to treatment with fluorouracil, epirubicin, and cyclophosphamide (FEC)." (PMID 35453789, 2022). "We found weak evidence for the association of risk variants rs294174 (ESR1), rs16886165 (MAP3K1), rs2214681 (CNTNAP2), rs4237855 (VDR), rs9594579 (RANKL), rs8183919 (PTGIS), rs2981582 (FGFR2), and rs1799950 (BRCA1) with sporadic breast cancer." (PMID 33126731, 2020). "Moreover, the IL-6/STAT3/JAK2 pathway is involved in the maintenance of stem cell–like cancer cells because CD44+CD24+ and CD44+CD24− breast cancer cells have high phospho-STAT3 via their expression of genes such as IL6, PTGIS, and HAS1, which activate an autocrine loop." (PMID 26515594, 2015).
liver fibrosis (9 papers, 2018 to 2024). "We further investigated the function of PTGIS in liver fibrosis by Recombinant Hepatic-adeno-associated virus (rAAV8)-PTGIS overexpression." (PMID 29892223, 2018). "In this study, we sought to define the potential roles of PTGIS in regulating HSCs activation and survival and the molecular mechanism underlying this regulation in liver fibrosis." (PMID 29892223, 2018). "Additionally, PTGIS methylation has been implicated in promoting liver fibrosis, and PTGIS has been found to protect hematopoietic stem cells in specific conditions." (PMID 37796199, 2023). "In general, it is worth doing further studies to explore whether PTGIS have effect on HCs apoptosis and kupffer cells activation and the underlying molecular mechanism in the progress of liver fibrosis." (PMID 29892223, 2018). "DNMT1 and DNMT3B methylates the genes encoding regulator of calcineurin 1 (RCAN1), prostacyclin synthase (PTGIS), Septin9 and SAD1/UNC84 domain protein-2 (SUN2), promoting HSC activation and liver fibrosis." (PMID 34805276, 2021). "Expression of PTGIS has been shown to be decreased in the liver of mice with hepatic fibrosis compared to wild mice." (PMID 32311840, 2020). "The pilot experiments showed that the promoter of prostacyclin synthase (PTGIS) gene was hypermethylated in CCl4-induced liver fibrosis mouse model." (PMID 29892223, 2018). "As far as we know, this is the first investigation about PTGIS hypermethylation in progression of liver fibrosis in vivo and in vitro." (PMID 29892223, 2018). "Taken together, these data indicated that the downregulation of PTGIS in liver fibrosis was attributed to DNA methylation and PTGIS gene methylation was mainly caused by DNMT1 and DNMT3b." (PMID 29892223, 2018). "In the previous study of our laboratory, the genomic methylation analysis results shown that PTGIS gene was methylated in mice with liver fibrosis." (PMID 29892223, 2018). "This study suggests a therapeutic role of PTGIS in liver fibrosis and encourages further studies to determine the value of PTGIS as a novel biomarker in hepatic fibrosis." (PMID 29892223, 2018). "Taken together, these data indicated that downregulation of PTGIS in hepatic fibrosis was attributed to hypermethylation of PTGIS promoter which mainly induced by DNMT1 and DNMT3b." (PMID 29892223, 2018). "Taken together, these data indicated that liver fibrosis mice model were well established and PTGIS expression was decreased in CCl4-induced mice model." (PMID 29892223, 2018). "Our experiment results suggested that DNA methylation of PTGIS plays a pivotal role in the progression of liver fibrosis and HSCs activation." (PMID 29892223, 2018). "DNA methylation of PTGIS plays an important role in the progression of liver fibrosis and activation of HSCs, implying that targeting PTGIS has a therapeutic potential ability to treat liver fibrosis." (PMID 37056286, 2023). "Notably, PTGIS expression is elevated in the early stages of CCl4-induced liver fibrosis mice models only to be downregulated at a later stage." (PMID 37056286, 2023). "The second transcript (PTGIS) catalyzes the biosynthesis and metabolism of eicosanoids; its overexpression was reported to prevent the development of murine lung tumors, inhibit the activation of HSCs and alleviate liver fibrosis in mice." (PMID 34439473, 2021). "Forced PTGIS expression in vivo through tail vein injection rAAV8-PTGIS can alleviate liver fibrosis, which was certified by the decreased COL1a1 and α-SMA protein and mRNA expression levels in primary HSCs isolated from fibrotic mice and the downregulated serum ALT/AST levels." (PMID 29892223, 2018). "Accordingly, we supposed that forced PTGIS expression in vivo and in vitro may alleviate liver fibrosis through affect HSCs activation and survival." (PMID 29892223, 2018). "The data presented indicated that adding PTGIS expression in vivo could alleviate CCl4-induced HSCs activation and liver fibrosis in mouse model." (PMID 29892223, 2018).
liver fibrosis (continued). "Therefore, our study unveils the role of PTGIS in HSCs activation, which may provide a possible explanation for CCl4-mediated liver fibrosis." (PMID 29892223, 2018). "As DNMT plays an important role in DNA methylation, DNMT inhibition may block the hypermethylation and downregulate related genes (such as PTGIS, PTEN, and Smad2/Smad3), inhibit the activation and proliferation of HSCs, inhibit the expression of α-SMA and COL1A1 in vitro, and delay liver fibrosis." (PMID 37056286, 2023). "Nevertheless, it is not clear whether changes in PTGIS expression is involved in liver fibrosis." (PMID 29892223, 2018).
colorectal cancer (8 papers, 2016 to 2024). A primary or metastatic malignant neoplasm that affects the colon or rectum. "One study found that the expression of PTGIS gene in colorectal cancer tissues was significantly lower than that in normal colorectal cancer tissues, and the high expression of PTGIS gene was associated with poor prognosis of patients." (PMID 39060344, 2024). "In this work, we used a bioinformatics database to analyze the correlation between the PTGIS gene and the occurrence and development of colorectal cancer." (PMID 37779109, 2023). "The frequency of genetic variation of PTGIS gene in the list of tumor types was analyzed in different tumor samples, The most frequent change of PTGIS (> 8%) occurred in patients with colorectal cancer, and “amplification” was the primary type of alteration." (PMID 37779109, 2023). "There are a total of 361 samples analyzing the effects of PTGIS gene expression in colorectal cancer patients in the GEPIA2 database, including 181 high-expression samples and 180 low-expression samples." (PMID 37779109, 2023). "Compared with normal colorectal cells (FHC), the expression of PTGIS mRNA was lower in colorectal cancer cells (HCT8, SW480)." (PMID 37779109, 2023). "The mechanism of the PTGIS gene involved in colorectal cancer progression needs further investigation." (PMID 37779109, 2023). "Further study on the relationship between PTGIS Gene and colorectal cancer is of great significance for finding highly specific markers for early detection of colorectal cancer and providing new targets for subsequent treatment of colorectal cancer." (PMID 37779109, 2023). "It was found that the expression of the PTGIS gene was different in normal colorectal tissues and colorectal cancer tissues." (PMID 37779109, 2023). "Analysis of the PTGIS gene in this study provides a theoretical basis for further exploring the pathogenesis of colorectal cancer and finding more accurate new targets for early screening and treatment of the cancer." (PMID 37779109, 2023). "At present, there are few studies on the role of the PTGIS gene in the pathogenesis of colorectal cancer." (PMID 37779109, 2023). "It has been reported in the literature that hypermethylation of gene promoters leads to transcriptional silencing as a common event in cancer, and hypermethylation of the PTGIS promoter was also detected in colorectal cancer." (PMID 32463792, 2020). "It has been demonstrated that PTGIS was hypermethylated in colorectal cancer and misregulation of PTGIS leads to the accumulation of pro-inflammatory signals." (PMID 29892223, 2018). "The decreased expression of hypermethylated WNT2B and PTGIS are novel findings both in the context of fibrosis and CD, though hypermethylation of the PTGIS promoter has been described as a feature of colorectal cancer." (PMID 27303667, 2016). "In colorectal cancer, PTGIS dysregulation may contribute to chromosomal instability and tumor progression." (PMID 37628631, 2023). "The mechanism of the PTGIS gene involved in the progression of colorectal cancer needs further." (PMID 37779109, 2023). "It has been found that PTGIS may be related to the occurrence of the EMT mechanism in colorectal cancer." (PMID 37779109, 2023). "In conclusion, the PTGIS gene may play an important role in the development, invasive and prognosis of colorectal cancer, and may also play a special role in immune infiltration." (PMID 37779109, 2023). "Therefore, this study focuses on the relationship between PTGIS and colorectal cancer." (PMID 37779109, 2023). "However, the mechanism of action of the PTGIS gene in colorectal cancer is not fully understood." (PMID 37779109, 2023). "Overexpression of PTGIS inhibited apoptosis and promoted proliferation, invasion, and migration ability of SW480 colorectal cancer cells." (PMID 37779109, 2023). "We found that expression of the PTGIS gene in colorectal cancer tissue was lower than that in normal colorectal cancer tissue." (PMID 37779109, 2023).
colorectal cancer (continued). "Hypermethylation of the PTGIS promoter is a feature of colorectal cancer, but decreased expression of PTGIS has not previously been linked with IBD." (PMID 26973718, 2016).
colon cancer (7 papers, 2015 to 2025). "PTGIS overexpression is closely linked to liver metastasis and predicts a poor prognosis in colon cancer patients." (PMID 40989165, 2025). "PTGIS was highly expressed in colon cancer tissues and liver metastases and was associated with liver metastasis and poor prognosis of colon cancer." (PMID 36703911, 2023). "PTGIS is a prostacyclin synthase and is highly expressed in colon cancer liver metastasis." (PMID 39060344, 2024). "The expression of PTGIS is decreased in colon cancer, but increased after the application of the methylation inhibitor DAC, indicating that methylation of the PTGIS gene contributes to the reduction in PTGIS gene expression." (PMID 37056286, 2023).